CORT (cortistatin)
Description:
Precursor of neuropeptides that bind to all somatostatin receptor (SSTR) subtypes. Inhibits cAMP production induced by forskolin through SSTRs. [Cortistatin-14]: Neuropeptide with neuronal depressant and sleep-modulating properties (By similarity). Acts as a ligand for MRGPRX2 receptor in mast cells.
Synonyms: MGC32686; SST2; CST-14; CST-17; CST-29
Tractability: Small molecule: a structure with a bound ligand is known. Antibody: its Gene Ontology location is reachable by antibodies, with high confidence; UniProt places it where antibodies can reach, with medium confidence; UniProt predicts a signal peptide or a membrane-spanning region.
Gene: Protein-coding gene on chromosome 1 (10,450,031 to 10,451,998, forward strand). Ensembl gene ENSG00000241563.
Subcellular location: Secreted; Secreted (Cortistatin-14)
Pathways (Reactome):
Signal Transduction: G alpha (i) signalling events; Peptide ligand-binding receptors
Gene Ontology:
Molecular function: G protein-coupled receptor binding; neuropeptide hormone activity; protein binding; hormone activity; receptor ligand activity
Biological process: adenylate cyclase-inhibiting G protein-coupled receptor signaling pathway; chemical synaptic transmission; regulation of cell migration
Cellular component: extracellular region; synapse
Genetic constraint (gnomAD): Loss-of-function variants: 2 observed, 4.4 expected, observed/expected ratio (o/e) 0.45, 90% interval 0.18 to 1.39. That is too few expected variants to judge how well the gene tolerates losing a copy. Missense variants: 158 observed, 138.65 expected, observed/expected ratio (o/e) 1.14, 90% interval 1 to 1.3. Synonymous variants: 72 observed, 63.13 expected, observed/expected ratio (o/e) 1.14, 90% interval 0.94 to 1.39.
Homologues: Orthologues: pig CORT (64% identical), rabbit CORT (57% identical), mouse Cort (56% identical), zebrafish cenps (8% identical). Paralogues in human: CENPS (12% identical).
Diseases named in the same sentence as CORT in open-access papers:
CORT is named in the same sentence as 40 diseases in open-access papers, as found by Europe PMC text mining. Sharing a sentence is not in itself a finding about the gene and the disease. The quoted sentences say what the papers report.
depression (17 papers, 2013 to 2025). "In humans, reductions in cortistatin expression were associated with cognitive defects observed in Alzheimer’s disease patients as well as with increased depression in patients with major depressive disorder." (PMID 39856044, 2025). "In comparison to the blunted stress response observed in Luman-deficient mice, patients suffering from depression show the opposite trend of low GR expression and increasing circulating CORT levels." (PMID 30337854, 2018). "Thus, elevated CORT may predict depression, and elevated morning CORT levels are associated with an increased risk of adolescent depression." (PMID 37700748, 2023). "Thus, CORT-induced model has been widely used as a chronic model of depression caused by stress." (PMID 35496273, 2022). "Urinary CORT levels in the depression group were elevated (159.30 ± 27.44 ng/mL vs. 209.80 ± 46.94 ng/mL, p < 0.01)." (PMID 40430140, 2025). "Behavioral test results of mice after injection of CORT suggested depression-like behavior, and serum levels of CORT, ACTH, and CRH increased dose-dependently and over time." (PMID 39539631, 2024). "Studies on mood disorders indicate that individuals exhibiting high depression symptoms have a reduced CORT/C-RP ratio—suggesting inadequate cortisol release relative to elevated C-RP and tend to experience worse stress-induced negative mood reactions." (PMID 38750102, 2024). "Studies have suggested that increased serum levels of CRH, CORT, and ACTH are associated with an increased risk of depression." (PMID 24367385, 2013). "Previous studies have shown that increased serum levels of CRH, CORT, and ACTH are associated with an increased risk of depression, suicide, and certain types of aggression." (PMID 24367385, 2013). "Upregulation of cortistatin in our female KOs in the present study might thus have led to the observed slightly better cognitive performance and the significantly reduced depression-like behavior after CS." (PMID 39856044, 2025). "Furthermore, CORT was reported to induce neuroinflammation and bring depression-like behaviors or other neuron dysfunction syndromes in the hippocampus, which indicated that the increase of CORT is a critical factor in the progression of SAE." (PMID 36147346, 2022). "The CORT model was more suitable for the study of depression caused by 5‐HT disorders, but it was not stable and might accumulate difficulties after long study duration." (PMID 31867894, 2020). "It was found that the secretion and response of CORT, the level of CRH in cerebrospinal fluid and inflammation increased in patients with severe depression." (PMID 39539631, 2024). "Late adolescent exposure to chronic variable stress (CVS) in female rats induced insufficient CORT and ACTH secretion and increased depression-like behaviors." (PMID 37700748, 2023). "It is well known that continuous activation of the HPA axis can induce abnormal increase of stress hormones such as CORT and ACTH, which has been considered to be closely related with cognitive dysfunction and depressive disorders in rodents and humans." (PMID 26458255, 2015). "This antidepressive effect of Xiangshao granule appeared to be related to decreased serum levels of CRH, CORT, and ACTH in the mouse depression model used." (PMID 24367385, 2013). "Serum CRH, CORT, and ACTH levels were significantly increased in depression mice compared with control (P < 0.05) and the expression levels of hippocampal BDNF and TrkB were reduced in the model group (P < 0.05)." (PMID 24367385, 2013). "Interestingly, Xiangshao granule treatment significantly decreased the serum levels of CRH, CORT and ACTH in the depression mouse model (P < 0.05)." (PMID 24367385, 2013).
depression (continued). "Collectively, our study demonstrates that Xiangshao granule has a significant antidepressant effect in the mouse depression model with its desired therapeutic effect possibly achieved through increasing hippocampal BDNF and TrkB expression and downregulating serum CRH, CORT, and ACTH levels." (PMID 24367385, 2013). "Our previous study has proposed the hypothesis that SOCG may control the hyperactivity of the HPA axis since SOCG downregulated the plasma levels of CORT, which is a major HPA axis-related stress-responding hormone, in a mouse model of stress-induced depression." (PMID 33224257, 2020).
Anxiety (15 papers, 2013 to 2025). Intense feelings of nervousness, tension, or panic often arise in response to interpersonal stresses. "The ACTH and CRH levels increased significantly in the serum and brain of the rats in the anxiety group, and the serum CORT levels were also significantly higher in these rats." (PMID 37686162, 2023). "Prairie vole fathers show increased anxiety-like behavior, and chronic pup exposure (in this case, 20 min of unrelated pup exposure per day for 10 days) results in an increase in basal CORT levels." (PMID 30568805, 2018). "Additionally, we observed high anxiety levels and poor maternal care along with reduced serum prolactin and elevated serum CORT concentrations in dams following MT17." (PMID 33758173, 2021). "Despite the anti-inflammatory actions of this neuropeptide, cortistatin-deficient mice were paradoxically resistant to EAE development, which was found to be associated to basal elevated circulating glucocorticoids and an anxiety-like behavior." (PMID 27357191, 2016). "This elevated anxiety level was manifested as a significant reduction in percentage of open arm duration (48.9% reduction; vehicle: 29.16 ± 3.08%, CORT: 14.89 ± 2.50%; P < 0.05) and number of open arm entry (55.2% reduction; vehicle: 23.90 ± 3.80, CORT: 10.70 ± 1.95; P < 0.05)." (PMID 24884833, 2014). "Cortistatin is involved in regulating hypothalamic pituitary axis (HPA) mediated stress responses in mice and mice lacking cortistatin showed increased levels of stress-related glucocorticoids and anxiety-like behavior." (PMID 39856044, 2025).
cognition impairment (4 papers, 2015 to 2025). "Indeed, treatment with lysed Lactobacillus can have bioactivity, such as improving affective/cognitive impairments and decreasing CORT levels." (PMID 39520540, 2025).
Obesity (4 papers, 2012 to 2016). Accumulation of substantial excess body fat. "Our results also suggest that SST, and possibly CORT, might play a pivotal role in the pathological association between obesity-associated changes and MG tumorigenesis." (PMID 26956474, 2016). "In contrast, under obesity conditions, CORT-KO and SST-KO had a similar percentage of mammary tumors, although latency in tumor development was lower in CORT-KO than in SST-KO mice." (PMID 26956474, 2016). "HF-diet modestly increased the sensitivity to DMBA-induced carcinogenesis in control mice, whereas, as observed in LF-fed CORT-KO, HF-fed CORT-KO mice exhibited aggravated tumor incidence, discarding a major influence of obesity on these CORT actions." (PMID 26956474, 2016). "Since obesity alters the expression of these systems in different tissues and is associated to MG (patho) physiology, we sought to investigate the role of SST/CORT in regulating GH/IGF-I system in the MGs of lean and obese mice." (PMID 25806796, 2015). "In relation to CORT, and based on its described anti-inflammatory properties, it would be of interest to explore its role on the inflammatory signaling that occurs during obesity conditions." (PMID 23162532, 2012). "To unveil the putative interplay between SST or CORT and obesity, we firstly analyzed BW gain and body composition in male and female SST-KO, CORT-KO and their littermate WT-controls fed a LF- or a HF-diet." (PMID 27901064, 2016). "To analyze the effect of diet-induced obesity and the implication of SST and CORT in the regulation of GH/IGF-I, SST/CORT and ghrelin systems expression in the MFPs, we used CORT- and SST-KO female mice and their respective control fed a LF or HF diet." (PMID 25806796, 2015). "To further explore the putative causes underlying the differences observed in DMBA-induced tumor incidence, we investigated the effect of diet-induced obesity and lack of CORT or SST in MG development, by analyzing MG complexity and the number of TEBs on whole mounts." (PMID 26956474, 2016). "We analyzed the interaction of diet-induced obesity with the lack of SST and CORT on the production and secretion of key pituitary hormones by determining GH, IGF and PRL levels at sacrifice." (PMID 27901064, 2016).
lung carcinoma (2 papers, 2020 to 2022). "CORT is an endogenous cyclic neuropeptide, which can regulate the growth and metastasis of lung cancer and thyroid cancer, and regulate inflammation by inhibiting immune infiltration." (PMID 35075228, 2022). "CORT is an endogenous cyclic neuropeptide that can regulate the growth and metastasis of lung cancer and thyroid cancer, and it also regulates the inflammatory response by inhibiting the immune infiltration." (PMID 33110201, 2020).
neuroblastoma (2 papers, 2002 to 2004). Neuroblastoma (NB) is the most common solid, extracranial childhood tumor. "A gene was predicted to reside distal to the CORT gene but proximal to the PGD gene, in the neuroblastoma tumour suppressor gene candidate region on chromosome 1p36.22." (PMID 15328517, 2004).
thyroid cancer (2 papers, 2022 to 2023). "CORT is an endogenous cyclic neuropeptide known to regulate the growth and metastasis of lung and thyroid cancer." (PMID 37046795, 2023).
amnesia (1 paper, 2013). Pathologic partial or complete loss of the ability to recall past experiences ( AMNESIA, RETROGRADE) or to form new memories ( AMNESIA, ANTEROGRADE). "In other words, rats make a precocious transition from the infantile amnesia system to the adult-like retention system following exposure to stress/CORT." (PMID 23964249, 2013).
atherosclerosis (1 paper, 2017). A disease characterized by the build-up of fatty material and calcium deposition in the arterial wall resulting in partial or complete occlusion of the arterial lumen. "An important question that needs to be addressed is which role is played by endogenous cortistatin in the regulation of atherosclerosis." (PMID 28406244, 2017). "The present study shows that treatment with cortistatin regulated the presence of SMCs in the plaque and intimal/medial ratio in carotid and aorta, suggesting that cortistatin could limit the outward vascular remodelling observed during the progression of atherosclerosis." (PMID 28406244, 2017).
autism spectrum disorder (1 paper, 2021). A spectrum of developmental disorders that includes autism, and Asperger syndrome. "MRGPRX2 is a receptor with multiple neuropeptide ligands, including cortistatin-14, and this receptor’s role was noted in a review of molecular mechanisms of autism spectrum disorder." (PMID 33834688, 2021).
autoimmune disease (1 paper, 2017). A disorder resulting from loss of function or tissue destruction of an organ or multiple organs, arising from humoral or cellular immune responses of the individual to their own tissue constituents. "Cortistatin is a neuropeptide expressed in the vascular system and atherosclerotic plaques that regulates vascular calcification and neointimal formation, and inhibits inflammation in different experimental models of autoimmune diseases." (PMID 28406244, 2017).
benign prostatic hyperplasia (1 paper, 2022). A non-cancerous nodular enlargement of the prostate gland. "Consistently, endogenous CORT was overexpressed in PCa samples (compared with benign-prostatic-hyperplasia) and correlated with key clinical (i.e., metastasis) and molecular (i.e., SSTR2/SSTR5 expression) parameters." (PMID 36361790, 2022).
breast carcinoma (1 paper, 2016). "Specifically, 10.25 % of WT mice developed a DMBA-induced mammary tumor, whereas 33.33 % of CORT-KO mice had tumors." (PMID 26956474, 2016). "Somatostatin (SST) and cortistatin (CORT), two highly related pleiotropic neuropeptide hormones, have been shown to inhibit proliferation and invasion of breast cancer and other cell types, suggesting their potential value to treat various endocrine-related tumors." (PMID 26956474, 2016). "On the other hand, although the actions of CORT have commonly been assumed to be similar to those exerted by SST at many levels, the potential role of CORT in the control of breast cancer development and progression has not been studied hitherto." (PMID 26956474, 2016). "However, the elevated incidence of mammary tumors in CORT-KO mice would suggest that elevated SST does not seem sufficient to compensate for the lack of endogenous CORT." (PMID 26956474, 2016).
coronary artery disease (1 paper, 2017). "We concluded that CorT is associated with increased pro-inflammatory processes related to coronary artery disease." (PMID 28470327, 2017).
diabetes (1 paper, 2021). "Surprisingly, CoRT was found to have distinct effects on the progression of insulitis in NOD mice treated at diabetes onset versus a late preclinical T1D stage." (PMID 34314385, 2021).
essential hypertension (1 paper, 2017). Hypertension that presents without an identifiable cause. "Therefore CorT may be one of the forms of artery remodelling induced by hypertension due to increased coronary pressure and blood flow." (PMID 28470327, 2017).
glioblastoma (1 paper, 2025). The most malignant astrocytic tumor (WHO grade IV). "A clear downregulation of the whole somatostatin/cortistatin-system (except for SSTR5) in glioblastoma vs. non-tumour brain samples was demonstrated, with high discriminatory capacity." (PMID 40268793, 2025).
injury (1 paper, 2016). Damage inflicted on the body as the direct or indirect result of an external force, with or without disruption of structural continuity. "A significant diurnal oscillation in plasma CORT levels was also observed in male sham+PSL mice on day 7 after nerve injury (F5,30=6.592, P<0.001)." (PMID 27739425, 2016).
migraine (1 paper, 2022). "Neuropeptides directly associated with pain or migraine from significantly differentially expressed neuropeptide prohormone genes include apelin (APLN), cortistatin (CORT), IGF2, neuromedin B (NMB), neuropeptide W (NPW), PDGFA and platelet-derived growth factor, D polypeptide (PDGFD), TAC4, and VIP." (PMID 35453627, 2022).
osteosarcoma (1 paper, 2023). A usually aggressive malignant bone-forming mesenchymal neoplasm, predominantly affecting adolescents and young adults. "We demonstrated the results by IHC experiments, and observed that CGREF1, CORT and RHBDL2 proteins expression were high in the tissue of osteosarcoma patients, while the proteins were lowly expressed in normal tissue." (PMID 37441535, 2023).
proliferative diabetic retinopathy (1 paper, 2008). Advanced retinopathy due to diabetes mellitus characterized by the formation of new vessels in the retina. "Cortistatin (CST), a neuropeptide with strong structural and functional similarities to somatostatin, is abundant in the vitreous fluid, and it is decreased in patients with proliferative diabetic retinopathy." (PMID 18709137, 2008).
Sepsis (1 paper, 2022). Sepsis is defined as life-threatening organ dysfunction caused by a dysregulated host response to infection. "Among these, decreased expression of cortistatin mRNA in the brains of SAE mice compared to sham mice in the acute phase of sepsis was identified (three days after peritoneal contamination and infection [PCI]; fold change = 0.482, t = 11.92, P = 2.33 × 10−7, adjusted P = 1.67 × 10−4)." (PMID 36148090, 2022).
tumor (6 papers, 2004 to 2025). "Targeting the somatostatin/cortistatin-system is considered a successful avenue for treating different tumour pathologies." (PMID 40268793, 2025). "CORT, an endogenous cyclic neuropeptide, can modulate inflammatory responses by inhibiting immune infiltration and promoting tumor growth and metastasis." (PMID 37031292, 2023). "Strikingly, analysis from the available Grasso in silico cohort revealed that endogenous CORT expression was higher in metastatic PCa samples compared to primary tumors and non-tumor samples." (PMID 36361790, 2022). "Remarkably, we also found that endogenous CORT expression was higher in metastatic PCa samples compared to primary tumors and non-tumor samples." (PMID 36361790, 2022). "Of note, on comparison of both KO mice models there was a strikingly higher proportion of MG tumors, and higher tumor multiplicity, in LF-fed CORT-KO compared to LF-fed SST-KO mice." (PMID 26956474, 2016). "Interestingly, HF-fed CORT-KO mice had levels of tumor incidence, latency, multiplicity, and burden that were numerically, but not significantly lower than those observed in lean CORT-KO." (PMID 26956474, 2016). "Somatostatin (SST) and cortistatin (CORT), two structurally and functionally related peptides, share a family of widespread receptors (sst1-5) to exert apparently similar biological actions, including endocrine/metabolic regulation and suppression of tumor cell proliferation." (PMID 26956474, 2016). "Interestingly, CORT-KO mice on a LF diet had clearly elevated circulating GH levels, which may contribute, at least in part, to the increased tumor incidence and multiplicity observed in these mice; however, other additional factors should be also considered." (PMID 26956474, 2016). "In fact, whole-mount analysis indicated that HF-feeding significantly increased ductal mammary hyperplasia in CORT-KO mice, but did not influence tumor formation." (PMID 26956474, 2016). "This implies that the tumor-suppressive function of ERRFI1 can no longer effectively mitigate the pro-tumorigenic effects of CORT in metastatic BCa and may be attributed to the impaired CORT-mediated induction of ERRFI1 in this cell line." (PMID 32432675, 2020).